GSDMD (gasdermin D)
Diseases named in the same sentence as GSDMD in open-access papers (continued):
Sharing a sentence is not in itself a finding about the gene and the disease.
tumor (continued). "It remains to be tested if ESCRT-mediated membrane repair is responsible for the tumor-promoting role of GSDMD in sporadic CRC, and if abolishing this process will revert the function of GSDMD in causing tumor cell death and tumor inhibition." (PMID 38898209, 2024). "Released Orz boosts tumor immunogenicity by upregulating GSDMD and PD-L1 expressions, while released AMPCP curtails ADO accumulation by inhibiting CD73." (PMID 39221221, 2024). "We ablated GSDMD in the whole body and in hematopoietic cells in these CRC models, and now report a tumor-promoting role of GSDMD in sporadic CRC that is dependent on NLRP3 and gut bacteria." (PMID 38898209, 2024). "The expression of GSDMD was significantly and positively correlated with the GSDMD expression was significantly and positively correlated with the tumor purity of LIHC and the degree of infiltration of CD4+ T cells." (PMID 38434972, 2024). "GSDMD is involved in various pyroptosis signaling pathways, highlighting its intricate role in mediating the pyroptosis of tumor cells." (PMID 38304430, 2024). "From OC tumor samples study, we demonstrated patients with high gasdermin D (GSDMD) expression in omental adipocytes is highly correlated with chemoresistance and poor outcome in advanced-stage OC." (PMID 38862973, 2024). "In CRC models, RT suppressed the expression of miR-15a while inducing caspase-1 activity and GSDMD expression, decreasing tumor cell vitality, proliferation, and growth." (PMID 39062587, 2024). "We further engineered a minimal tumor-agnostic inducible system for chemically controlled triggering of GSDMD-mediated pyroptosis, that would enable system introduction with a single electroporation, which would be beneficial for therapeutic use." (PMID 39737979, 2024). "As a key executor of pyroptosis, the gasdermin family, particularly GSDMD, plays a pivotal role in anti-tumor immunity." (PMID 39587093, 2024). "For the assessment of pyroptosis-induced tumor surveillance we employed NT GSDMD, therefore, omitting the need for an additional cleavage of full-length GSDMD." (PMID 39737979, 2024). "Ablation of GSDMD in a mouse model of sporadic colorectal cancer resulted in reduced tumor formation in the colon and rectum, suggesting a tumor-promoting role of the protein in the gut." (PMID 38898209, 2024). "When endometrial or ovarian cancer cells are exposed to the reversible acetylcholine transferase inhibitor α-NETA, there is an induction of pyroptosis through the GSDMD/caspase-4 mechanism, leading to suppressed tumor growth in mouse models." (PMID 38304430, 2024). "In cases of endometrial carcinoma, tumor cells display elevated expression levels of GSDMD compared to their healthier counterparts." (PMID 38304430, 2024). "In terms of tumor grade, the expression level of GSDMD gradually increased from tumor grade 1 to 4 and all were higher than in normal tissues." (PMID 39607202, 2024). "Here, GSDMD was attached to the exosome surface by the exosome membrane protein BASP1 to increase the content of GSDMD in tumor cells." (PMID 38762500, 2024). "Specifically, there is an exploration into antagonists designed to inhibit GSDMD activity, aiming to effectively modulate tumor immune responses." (PMID 38304430, 2024). "Transcriptome sequencing results and western blot analysis demonstrated the Caspase‐1/GSDMD‐dependent pyroptosis pathway induced by sonopiezocatalytic effect, ultimately leading to tumor cell death and achieving tumor suppression." (PMID 39248778, 2024). "Analysis of tumour lysates using Western blotting showed elevated Cleaved GSDMD, indicative of pyroptosis, in the combination therapy group but not in the single‐agent groups for both PDX models." (PMID 38804602, 2024). "Emerging evidence has revealed that various anticancer therapies can elicit GSDMD‐dependent tumour cell pyroptosis by activating the NLRP3 inflammasome, including chemotherapy and targeted therapy." (PMID 38804602, 2024).
tumor (continued). "Activation of ROS can induce inflammation or activate caspase-3, resulting in the cleavage of GSDMD/E and triggering pyroptosis in tumor cells, thereby exhibiting anti-tumor effects." (PMID 39011036, 2024). "It turns out that GSDMD is a component necessary for anti-tumor immunity by mediating an optimal CTL response to cancer cells." (PMID 38553639, 2024). "GSDMD knockdown has been shown to activate Caspase-3 cleavage in lung cancer cells of mouse, inducing the inhibition of tumor growth in mice." (PMID 39058145, 2024). "Consistent with this notion, ablation of GSDMD in hematopoietic cells did not result in an observable reduction in the full-length or cleaved GSDMD levels in the whole tumor." (PMID 38898209, 2024). "Second, while GSDMD-deficient models validated DMB’s efficacy, broader testing across various tumor types and physiological conditions is essential." (PMID 39587093, 2024). "We developed a minimalistic small molecule-induced system that enables potent, tumor expression profile-independent induction of GSDMD-mediated pyroptosis and antitumor responses." (PMID 39737979, 2024). "As seen in patients, the role of GSDMD in mouse models of cancer seems to depend on the tumor type and the context." (PMID 39224600, 2024). "This led to our initial expectation that GSDMD should kill cancer cells when activated, and thus serve as a tumor-suppressing factor." (PMID 38898209, 2024). "DMB represents a groundbreaking approach to cancer treatment by activating GSDMD-mediated pyroptosis and enhancing anti-tumor immunity." (PMID 39587093, 2024). "Remarkably, the whole tumor transcriptome analysis revealed that IL-12 enriched pyroptosis and NT GSDMD + IL-1β + IL-18 treatments with different therapeutic outcomes exhibit enrichment in interferon signaling." (PMID 39737979, 2024). "The pyroptotic capacity of in-situ electroporated NT GSDMD was confirmed with an increased number of PI-positive tumor cells in the NT GSDMD-treated tumors compared to empty vector-treated control." (PMID 39737979, 2024). "A nanoparticle-mediated cytotoxic drug can selectively be delivered to cancer cells via exotoxin A to activate NLRP3, cleave GSDMD, and mediate pyroptosis at the primary tumor site." (PMID 39062587, 2024). "Overall, these observations demonstrated that REGγ inhibition promoted pyroptosis through the indirect regulation of GSDME and GSDMD in both macrophages and tumor cells." (PMID 39349939, 2024). "This complexity underscores the challenge of precisely delineating the mechanisms through which GSDMD induces pyroptotic cell death within the tumor microenvironment." (PMID 38304430, 2024). "The downregulation of GSDMD expression in gastric cancer cells promotes tumor progression, possibly through the activation of the PI3K/PKB signaling pathway and the expedited transition of S/G2 cells." (PMID 38304430, 2024). "They underscore the complex role of inflammatory pathways in cancer, emphasizing the need for further exploration into the multifaceted effects of GSDMD in various tumor microenvironments." (PMID 39224600, 2024). "Elevated levels of gasdermin D expression has been observed to potentially correlate with more aggressive tumour features or poor prognosis." (PMID 39766111, 2024). "Our results demonstrate that inducing GSDMD-mediated pyroptosis in immunologically silent tumors leads to tumor regression and improves long-term, tumor-free survival in treated mice." (PMID 39737979, 2024). "Cleavage and activation of GSDMD were found in both epithelial-derived tumor cells and tumor-infiltrating immune cells, but the former population represents predominant site of GSDMD activation." (PMID 38898209, 2024). "More recently, Alisol A, a marine herb with anti-tumor effects, was found to induce pyroptosis by increasing the levels of caspase-1, GSDMD, and GSDME in CRC cells, while reducing cancer cell migration and increasing the chemosensitivity of cisplatin." (PMID 39062587, 2024).
tumor (continued). "Lymph node metastasis had significant difference with the CASP4 and GSDMD expression (P < 0.05); tumor volume had significant difference with CASP1 and CASP5 expression (P < 0.05)." (PMID 37194012, 2023). "Significantly higher expression of NLRP3 and (NT-)GSDMD were observed in knockdown-LINC00969 derived tumours treated with gefitinib." (PMID 37156816, 2023). "It reveals a general function of tumor‐cell GSDMD‐induced pyroptosis in enhancing anticancer immunity." (PMID 37125240, 2023). "Considering the role of GSDMD in the modulation of immune-related signaling pathways, we analyzed the relationship between GSDMD and the tumor immune microenvironment." (PMID 37371484, 2023). "While GSDMD-dependent pyroptosis has been shown to promote tumor cell death and inhibit the proliferation of gastric cancer cells, its role in other types of tumors is more complex." (PMID 37275856, 2023). "We also found that the activity of tumor proliferation signature and angiogenesis pathways was upregulated with the increase in GSDMD expression (p < 0.0001)." (PMID 37371484, 2023). "Highly expressed GSDMD promoted a permissive microenvironment for tumor growth by upregulating the ratio of CAFs and macrophages in the TME." (PMID 37371484, 2023). "The expression of GSDMD in cytotoxic T cells is positively correlated with its ability to eliminate tumor cells." (PMID 37859811, 2023). "Knockdown of GSDMD inhibits tumor growth through promoting the mitochondrial apoptotic pathway and inhibiting epidermal growth factor receptor (EGFR)/AKT signaling." (PMID 36932407, 2023). "A bacterium‐attenuated S. typhimurium (VNP) system is developed to deliver GSDMD into murine 4T1 tumor cells to initiate GSDMD‐triggered pyroptosis for immunotherapy." (PMID 37125240, 2023). "The demonstration that pyroptosis can also trigger anti-tumor immunity makes GSDMD an attractive target for tumor intervention, and the clear connection between infection and inflammasome activation makes GSDMD a promising target for anti-infection treatment." (PMID 37495617, 2023). "Reduced GSDMD expression speeds up tumor proliferation and S/G2 transition of cells by stimulating the STAT3 and PI3K/PKB pathways." (PMID 37752941, 2023). "GSDMD-mediated pyroptosis accompanies the release of the pro-inflammatory cytokine IL-1β,26,39 which supports the tumor-specific T helper 1 cell-mediated immune response against cancer." (PMID 36699618, 2023). "NF-κB and signal transducers and activators of transcription 1 (STAT1) can also induce pyroptosis by regulating Caspase-1 or GSDMD protein expression, accompanied by a large release of inflammatory factors, which acts as a tumor growth suppressor." (PMID 36744134, 2023). "GSDMD (p = 0.012) and IL-18 (p < 0.001) were highly expressed in tumor tissues, whereas NLRP3 (p < 0.001) and CASP1 (p = 0.001) expression was low in tumor tissues." (PMID 37864196, 2023). "The role of GSDMD in cancer is complex and context-dependent, leading to diverse disease outcomes across different tumor types." (PMID 38002346, 2023). "Our previous study discovered that the gasdermin family members are involved in the occurrence and development of HCC, the expression of GSDMB and GSDMD is significantly higher in HCC tumor samples compared with corresponding normal samples." (PMID 37061535, 2023). "Although GSDMD inhibitors, disulfiram and Bay 11–7082, potently suppress pyroptosis, they show anti-tumor effects through inducing ferroptosis (by disulfiram) or apoptosis (by Bay 11–7082)." (PMID 36932407, 2023). "Our study demonstrated the anti-tumor effect of nigericin on TNBCs by inducing concurrent Caspase-1/GSDMD-dependent pyroptosis and Caspase-3-dependent apoptosis." (PMID 37370831, 2023). "In NSCLC, a higher expression level of GSDMD is related to invasive features, including an advanced tumour-node-metastasis stage and enlarged tumour size." (PMID 37337018, 2023).
tumor (continued). "Knockdown of GSDMD suppressed tumor proliferation by promoting the mitochondrial apoptotic pathway and inhibiting the EGFR/Akt signaling pathway in NSCLC." (PMID 37371484, 2023). "Downregulation of GSDMD in NSCLC has been shown to inhibit tumor proliferation through an intrinsic mitochondrial apoptotic pathway." (PMID 38002346, 2023). "Taxol and Δ‐Ru1 inhibit tumor development and adverse effects via caspase 1/GSDMD‐dependent pyroptosis." (PMID 37752941, 2023). "Variations in the composition of immune cells, stromal cells, and cytokine profiles within the tumor microenvironment can influence the expression and activation of GSDMD." (PMID 38002346, 2023). "In some cases, inflammasomes inhibit tumor progression by initiating GSDMD-mediated pyroptosis in cancer cells and stimulating IL-1 signal-mediated anti-tumor immunity." (PMID 36932407, 2023). "For instance, PRGs, including NLRP3, Gasdermin D (GSDMD), Caspase 1 (CASP1), and Gasdermin E (GSDME), are highly associated with oncogenesis as well as tumor progression." (PMID 37149620, 2023). "Paradoxically, another study showed that inhibition of GSDMD expression inhibited tumor cell proliferation in NSCLC." (PMID 37275856, 2023). "In colorectal cancer, GSDMD levels are decreased, and these levels are negatively correlated with tumor metastasis, tumor aggressiveness, and 5‐year survival rates." (PMID 37752941, 2023). "In a word, the anti-inflammation effects of GSDMD inhibitors have been repeatedly proven, but their applications in tumor development remain to be further evaluated." (PMID 36932407, 2023). "K3ZrF7:Yb/Er upconversion nanoparticles (ZrNPs), a pyroptosis inducer, induces tumor cell pyroptosis through the GSDMD/IL-1β pathway, leading to cell lysis." (PMID 37705746, 2023). "Different tumor microenvironments can influence the expression and activation of GSDMD through various potential mechanisms; immune cells, including T cells, macrophages, and dendritic cells, are present in the tumor microenvironment." (PMID 38002346, 2023). "Knockdown of GSDMD has been demonstrated to suppress tumor progression by promoting the mitochondrial apoptotic pathway and inhibiting the epidermal growth factor receptor (EGFR)/Akt pathway." (PMID 38066523, 2023). "GSDMD depletion suppresses tumor proliferation by accelerating apoptosis and restraining the EGFR/Akt signaling pathway in NSCLC." (PMID 38016064, 2023). "The downregulation of GSDMD in CRC tissues has been significantly related to tumor stage, nodal stage, lymph node invasion, and clinical stage, indicating that low expression of GSDMD is an independent unfavorable factor for the prognosis of CRC." (PMID 38002346, 2023). "The results revealed that GSDMD can increase the sensitivity of tumours to chemotherapy via ER stress instead of pyroptosis." (PMID 35289335, 2022). "The defect in GSDMD alleviated the cytolytic ability of CD8+ T cells, suggesting that GSDMD is essential in the immune response of tumor cells." (PMID 35912258, 2022). "It was clear that the toxicity presented in doxy-induced GSDMD-NT gene-modified tumor cells was completely dependent on the expression of GSDMD-NT." (PMID 36189310, 2022). "After invasion into the cells, the higher GSH level in the tumor cytoplasm will break the GSH responsive linkers in the protein cages, triggering the release of GSDMD proteins for subsequent tumor cell pyroptosis." (PMID 36280674, 2022). "A previous study reported that GSDMD is activated by the cleavage of Caspase-3 and induces pyroptosis in response to tumour chemotherapy drugs." (PMID 35246158, 2022). "Among all Gasdermin family proteins, membrane perforin Gasdermin D (GSDMD) acts as an effective executor of pyroptosis mainly in immune cells, while its function and working mechanism in tumor cells remain elusive." (PMID 36280674, 2022).
tumor (continued). "In this study, we genetically modified tumor cells to produce inducible overexpression of GSDMD-NT to provide a generally applicable induction method for tumor cell pyroptosis." (PMID 36189310, 2022). "Taking together, our research indicates that GSDMD promotes ER stress, enabling tumour cells to clear misfolded and unfolded proteins faster in an inflammatory environment, supporting the maintenance of cell homoeostasis and providing a survival advantage." (PMID 35289335, 2022). "Tumor cells were genetically engineered to inducibly overexpress GSDMD-NT and induce pyroptosis as a novel personalized tumor cell vaccine." (PMID 36189310, 2022). "In brief, GSDMD-NT expression induced pyroptotic TC-1 cells to significantly or even completely suppress the tumor growth in mice challenged with wild-type TC-1 tumor cells." (PMID 36189310, 2022). "We further intuitively observed NLRP3/Gasdermin D colocalization in luteolin-treated HT-29 cells and mouse tumour tissues by immunofluorescence." (PMID 36105214, 2022). "The view was expanded with the discovery of caspase-3-mediated gasdermin E (GSDME) cleavage in tumor cells induced by chemotherapeutic drugs, and caspase-8-related cleavage of GSDMD in mouse macrophages during Yersinia infection." (PMID 36209102, 2022). "In general, we successfully created a system for inducing pyroptosis in TC-1, 4T1, and CT26 tumor cell lines, in which the expression of GSDMD-NT was strictly controlled by the inducer doxy." (PMID 36189310, 2022). "Western blotting of transplanted tumours showed that the phosphorylation level of eIF2α was higher in transplanted tumours overexpressing GSDMD than in control tumours." (PMID 35289335, 2022). "More importantly, we reveal that both the dsRNA-interferon signaling and GSDMD-mediated pyroptosis are of critical importance to the increased anti-tumor immunity and improved immunotherapeutic efficacy in MLL4-ablated tumors." (PMID 36323669, 2022). "More importantly, LDH@ZnPc-mediated PDT can effectively initiate gasdermin D (GSDMD)-dependent pyroptosis of tumor cells." (PMID 36463229, 2022). "We found that CTSB secreted by tumor significantly promoted the activation of neutral caspase-11/GSDMD cells IVM directed at SDMX has greatly inhibited SDMX oligarchy and the subsequent GSMX core network." (PMID 36132145, 2022). "for the first time demonstrated the biological effects of GSDMD in NSCLC, and their clinical data showed LUAD and LUSC specimens had significantly higher GSDMD protein levels than matched neighboring tumor specimens." (PMID 36523974, 2022). "The plasmids lenti-vector, lenti-eGFP and lenti-GSDMD-NT were transduced into mouse tumor cells TC-1, 4T1, and CT26 respectively, followed by puromycin selection." (PMID 36189310, 2022). "Together, the results indicated that the in vivo induction of GSDMD-NT-mediated pyroptosis was effective enough to completely eliminate the established tumors from the inoculated genetically modified tumor cells." (PMID 36189310, 2022). "Honglin Yan also showed that Cisplatin (DDP) had the effect of an anti-tumor on TNBC, which is brought on by up-regulating MEG3 to cause pyroptosis in NLRP3/caspase-1/GSDMD manner." (PMID 36119049, 2022). "In this regard, VNP20009 (VNP) was selected as a carrier to shuttle GSDMD to the cytoplasm of tumor cells." (PMID 36280674, 2022). "A more interesting finding is that LDH@ZnPc-mediated PDT can induce GSDMD-dependent pyroptosis in tumor cells." (PMID 36463229, 2022). "GSDMD was found to be highly downregulated in human colorectal tumor samples and serves as an important prognostic molecule in tumor therapy." (PMID 36003332, 2022). "Our exploration found GSDMD appeared as an oncogene, because it was upregulated in the tumor tissue." (PMID 35153782, 2022).